HOXD10 (homeobox D10)
Description:
Sequence-specific transcription factor which is part of a developmental regulatory system that provides cells with specific positional identities on the anterior-posterior axis.
Synonyms: HOX4D; HOX4E; HOX4; Hox-4.4
Tractability: PROTAC: ubiquitination databases record sites on it.
Gene: Protein-coding gene on chromosome 2 (176,108,790 to 176,119,937, forward strand). Ensembl gene ENSG00000128710.
Subcellular location: Nucleus
Subcellular location (Human Protein Atlas): Nucleoplasm; Cytoplasmic bodies; Cytosol
Gene Ontology:
Molecular function: protein binding; sequence-specific double-stranded DNA binding; DNA-binding transcription factor activity, RNA polymerase II-specific; RNA polymerase II cis-regulatory region sequence-specific DNA binding; chromatin binding; DNA binding; DNA-binding transcription activator activity, RNA polymerase II-specific; DNA-binding transcription factor activity; RNA polymerase II transcription regulatory region sequence-specific DNA binding
Biological process: negative regulation of cell cycle; regulation of transcription by RNA polymerase II; positive regulation of transcription by RNA polymerase II; regulation of DNA-templated transcription
Cellular component: chromatin; nucleus
Genetic constraint (gnomAD): Loss-of-function variants: 15 observed, 28.66 expected, observed/expected ratio (o/e) 0.52, 90% interval 0.35 to 0.81. The upper end of that interval is the gene's LOEUF score, 0.81, which puts it in group 3 of 6, group 1 being the genes least tolerant of losing a copy. Missense variants: 440 observed, 454.09 expected, observed/expected ratio (o/e) 0.97, 90% interval 0.89 to 1.05. Synonymous variants: 178 observed, 167.7 expected, observed/expected ratio (o/e) 1.06, 90% interval 0.94 to 1.2.
Homologues: Orthologues: chimpanzee HOXD10 (100% identical), dog HOXD10 (100% identical), macaque HOXD10 (99% identical), rabbit HOXD10 (99% identical), pig HOXD10 (99% identical), guinea pig HOXD10 (99% identical), mouse Hoxd10 (99% identical), rat Hoxd10 (99% identical), zebrafish hoxd10a (69% identical). Paralogues in human: HOXA10 (49% identical), HOXC10 (44% identical), HOXD9 (27% identical), HOXC9 (27% identical), HOXB9 (26% identical), HOXC11 (21% identical), HOXC12 (21% identical), HOXD11 (20% identical), HOXA11 (19% identical), HOXD12 (19% identical), HOXD8 (18% identical), HOXB3 (18% identical), and 30 more.
Diseases named in the same sentence as HOXD10 in open-access papers:
HOXD10 is named in the same sentence as 80 diseases in open-access papers, as found by Europe PMC text mining. Sharing a sentence is not in itself a finding about the gene and the disease. The quoted sentences say what the papers report.
breast carcinoma (65 papers, 2009 to 2025). "In breast cancer, significant differences were found between cancerous and normal tissues, and low expression of HOXD10 was associated with high‐grade breast cancer, displaying a similar tumor suppressor function to that in gastric cancer." (PMID 28745433, 2017). "HOXD10, a sequence-specific transcription factor, has been intimately linked with the invasion and metastatic potential of human breast cancer cells." (PMID 25236186, 2014). "In breast carcinoma cell lines loss of HOXD10 expression occurs during malignant transformation and subsequent forced re-expression leads to a more organized, phenotypically ‘normal’ structure in three-dimensional culture." (PMID 25301728, 2014). "Abnormal HOX gene expression has been associated with breast cancer and HOXD10 was recently identified as a gene target for the initiation of breast cancer invasion and metastasis." (PMID 21637771, 2011). "Conversely, in breast cancer, miR-10b-5p promotes metastasis by targeting HOXD10, which leads to RHOC upregulation—a gene crucial for cell migration and invasion—altering the TME to favor metastatic dissemination." (PMID 39796267, 2025). "Previous studies showed that HOTAIR reverses EMT by inhibiting HoxD10 and reducing the expression of miR-7 in breast cancer." (PMID 37576402, 2023). "In particular, in a mouse mammary tumor model, silencing of miR-10b significantly increases the levels of its target, Hoxd10 leading to the inhibition of metastasis." (PMID 34179081, 2021). "Another example of miR interference is the downregulation of HOXD10 by miR-10b, which favours the invasive and metastatic behaviour of breast cancer cells." (PMID 33375038, 2020). "In breast cancer and gliomas, HOXD10 downregulation results in the downregulation of miR-7 and upregulation of p21-activated kinase 1 expression (PAK1), which culminates in higher aggressiveness of these cancer types facilitating invasion and metastasis." (PMID 33375038, 2020). "miR-10b is significantly upregulated in metastatic breast cancer cells and initiates cell migration and invasion in murine xenograft model of breast cancer by targeting the HOXD10 gene along with E-cadherin and Tiam1." (PMID 30871273, 2019). "The exosome-mediated transfer of miR-10b promotes cell invasion in breast cancer, suppressing the protein level of its target genes, such as HOXD10 (homeobox D10) and KLF4 (Krüppel-like factor 4)." (PMID 31752198, 2019). "By analyzing the mRNA microarrays from TCGA, we determined that LATS1/2 level was positively correlated with STARD13, CDH5, HOXD1, and HOXD10 levels in breast cancer tissues, respectively." (PMID 29848346, 2018). "Whereas, upregulated miR-10b was positively correlated with cell migration and invasion through targeting homeobox D10 (HOXD10) in breast cancer." (PMID 30309377, 2018). "Additional studies have suggested that miR-10b regulates invasion and metastasis in breast cancer by suppressing the translation of a targeting gene (HOXD10)." (PMID 28691018, 2017). "The expression of HOXD10 was lost during the malignant progression of breast cancer, while the expression of HOXD10 was increased in human head and neck cancer." (PMID 29075359, 2017). "Despite multiple relationships, our study provide solid evidences to outline the novel roles of STARD13-, CDH5-, HOXD1-, and HOXD10-3’UTRs in modulating breast cancer metastasis via competing for miR-9, miR-10b and miR-125b in vitro and in vivo." (PMID 26985770, 2016).
breast carcinoma (continued). "HOXD1 has been validated as a biomarker for diagnosis and prognosis of breast cancer via a functional hypermethylome screen, while HOXD10, as a direct target of miR-10b, suppresses cell migration and invasion in various types of cancer." (PMID 26985770, 2016). "And HOXD10 had been proved as the strong target of miR-10b in breast cancer and other cancers, which is consistent with our results, therefore the HOXD10 is also included as a positive control for miR-10b." (PMID 26985770, 2016). "For example, miR-10b is transcriptionally upregulated by Twist and induces tumor invasion and metastasis in breast cancers by targeting homeobox D10 (HOXD10)." (PMID 26989421, 2016). "In fibroblasts HOTAIR represses HOXD8-D11 by recruiting PRC2 and an inverse relationship between HOTAIR and HOXD10 was reported in breast cancer." (PMID 25994132, 2015). "In breast cancer miR-7 has been identified as a tumor suppressor due to the interaction between the miR-7–1 gene promoter and the transcription factor HoxD10." (PMID 26452132, 2015). "For instance, in breast cancer, microRNA-10b (miR-10b) promotes invasion and metastasis of tumor cells through regulation of HOXD10, E-cadherin, and syndecan-1." (PMID 26311318, 2015). "It has been reported that the miR-10b can induce tumor invasion and initiate metastasis in breast cancer by targeting HOXD10 and promotes migration and invasion through direct binding with 3′-UTR of KLF4 in human esophageal cancer cells." (PMID 25428807, 2014). "The genes indicated in breast cancer progression include HoxD10, B13, and A11 in lumbosacral part and HoxB2, D3, and D4 in cervical part." (PMID 24634677, 2014). "Expression of miR-10b, a miRNA that promotes breast cancer cell metastasis by inhibiting HoxD10, is regulated by the transcription factor Twist, a major regulator of the epithelial-to-mesenchymal transition." (PMID 25406066, 2014). "Homeobox D10 (HoxD10) plays important roles in the differentiation of embryonic cells and progression of breast cancer." (PMID 24386080, 2013). "Studies have demonstrated that HoxD10 inhibits the angiogenesis and cell motility in endometrial cancer (EC) and impairs the cell invasiveness of gastric and breast cancers." (PMID 24386080, 2013). "The homeobox transcription factor HOXD10 was identified as a tumor suppressor gene targeted by miR-10b in breast cancers recently." (PMID 22558405, 2012). "It has previously been reported that HOXA9, a paralog of HOXA10, is a tumor suppressor in breast cancer, and expression of HOXD10 in MDA-MB-231 significantly impaired migration." (PMID 22439757, 2012). "miR-10b, which targets HOXD10, was additionally shown to be down-regulated in all the breast carcinomas from metastasis-free patients." (PMID 21846369, 2011). "The HOXD10 gene represses the expression of genes involved in cell migration and extracellular matrix remodeling in breast cancer cells, and it is regulated by miR-10b." (PMID 19664288, 2009). "As expected, the five gynecomastia samples showed a weak cytoplasmic HOXD10 IHC positivity, whereas 8/10 male breast cancers samples showed HOXD10 moderate- strong cytoplasmic positivity with membranous reinforcement." (PMID 19664288, 2009). "Since we observed miR-10b to be downregulated in male breast cancers, we therefore decided to analyze HOXD10 expression in formalin-fixed paraffin-embedded tissue samples obtained from 10 male breast cancer patients and five gynecomastia patients." (PMID 19664288, 2009). "Meanwhile, HOXD9 could be regulated by miR-126, and miR-10b can interact with HOXD10 to promote breast cancer metastasis." (PMID 33428601, 2021). "The first reports associating miRNAs with metastasis came in 2007, with the demonstration that miR-10b was induced by Twist1 binding and could promote metastasis in breast cancer in vitro and in vivo through targeting of Homeobox D10 (HOXD10)." (PMID 31906022, 2019).
breast carcinoma (continued). "To investigate whether STARD13-correlated ceRNA network is involved in breast CSC formation, we first detected the expression levels of STARD13, CDH5, HOXD1, and HOXD10 in a pool of CSCs naturally arising within breast cancer cells." (PMID 29848346, 2018). "Furthermore, miR-10b exerted its oncogenic effects by directly targeting various tumor-associated genes, such as HOXD10, TBX5, KLF4, and PTEN, in breast cancer, pancreatic cancer, glioblastoma, and bladder cancer." (PMID 28691018, 2017). "In addition, lncRNA HOTAIR, which is highly expressed in metastatic breast cancers, accelerates the EMT-dependent metastasis of breast cancer by inhibiting miR-7 through HoxD10 inhibition." (PMID 27992370, 2017). "It is well established that in breast cancer, miR-10b suppress migration and invasion property by directly targeting HOXD10 and RHOC.It has been known that miR-10b also interacts with KLF4 to stimulate migration and invasion potential in esophageal squamous cell carcinoma." (PMID 27467502, 2016). "miR‐10b promoted breast cancer cell migration and invasion by inhibiting HOXD10 protein synthesis." (PMID 26833707, 2016). "This promotes us to explore the functions of STARD13-, CDH5-, HOXD1-, and HOXD10-3’UTRs in breast cancer metastasis and whether they possess the functions through acting as ceRNAs." (PMID 26985770, 2016). "In sum, these data testify our hypothesis that STARD13, CDH5, HOXD1, and HOXD10 may bind with miR-9, miR-10b and miR-125b to suppress breast cancer metastasis." (PMID 26985770, 2016). "HOXD10 has been reported to be regulated by miR-10b in human breast cancer." (PMID 25236186, 2014). "Our recent work has confirmed that STARD13, CDH5, HOXD1, and HOXD10 could co-regulate each other through competing for several shared miRNA binding sites, and thus formed a ceRNA network to coordinately inhibit breast cancer EMT and metastasis, which is denoted as STARD13-correlated ceRNA network." (PMID 29848346, 2018). "In breast cancer, however, miR-10b-5p promotes EMT by targeting HOXD10, increasing cell migration and invasion." (PMID 39796267, 2025). "For example, exosome-mediated miR-10b secretion inhibits the protein levels of its target genes (HOXD10 and KLF4) and enhances breast cancer cell invasion." (PMID 39744442, 2025). "HOXD10 and HOXD13 gene expressions have been found to be altered in primary breast cancers with respect to normal breast tissue, switching from off to on." (PMID 38907278, 2024). "Breast cancer cell-derived exosomes, miR-21 and -10b, can silence the expression of PTEN and homeobox D10 (HOXD10) in normal epithelial cells to induce tumor formation in a Dicer-dependent manner." (PMID 36624542, 2023). "For example, in breast cancer, HOTAIR downregulates HOXD10 favouring the invasive and metastatic behaviour." (PMID 33375038, 2020). "By inhibiting miR-10b and indirectly restoring the levels of its tumor suppressor targets HOXD10 and PTEN, linifanib decreased proliferation, invasion and migration of breast cancer and HCC cells." (PMID 30166612, 2018). "Here, we identify CDH5, HOXD1, and HOXD10 as putative STARD13 ceRNAs and they display concordant patterns with STARD13 in different metastatic potential breast cancer cell lines and tissues." (PMID 26985770, 2016). "We chose posterior HOXC genes HOXC11-13 located in close proximity to the HOTAIR transcript and posterior HOXD genes HOXD10-13, reported to be regulated by HOTAIR in normal fibroblasts and breast cancer mediating aggressive phenotype." (PMID 25994132, 2015). "Downregulated HOTAIR showed an anti-correlative relationship with both HOXD10 and miR-7 in MDA-MB-231 breast cancer cells and miR-7 was inversely correlated with HOTAIR expression in breast cancer patients." (PMID 26308064, 2015). "Subsequently, exosomal miR-10b could be taken up by different TNBC cells and suppress the protein levels of its target genes, such as HOXD10 and KLF4, thereby promoting breast cancer cell invasion." (PMID 38124743, 2023).
breast carcinoma (continued). "HOXD10, HOXA5, and SEC61G have all been shown to play an important role in breast tumorigenesis and were identified as potential biomarkers for the diagnosis of breast cancer." (PMID 36531217, 2022). "HOXD10 and MAN1A1 show an up-regulated gene expression in breast cancer." (PMID 21533145, 2011). "To summarize, STARD13, which is triggered by CDH5, HOXD1, and HOXD10 ceRNAs, stimulates Hippo signaling by acting as a ceRNA for upregulating the LATS1/2 and blocks the Rho GTPase/F-actin pathway, inhibiting YAP/TAZ and suppressing EMT and CSC development in breast cancer." (PMID 39170516, 2024). "Increasing numbers of genes involved in breast cancer have been found, including Ets-1 (E-twenty-six-1), PKC (protein kinase C), CEP4 (CDC42 effector protein 4), Her2 (erb-b2 receptor tyrosine kinase 2), ALDH1 (aldehyde dehydrogenase 2), FOXA1 (forkhead box A1) and HOXD10 (homeobox D10)." (PMID 25739083, 2015). "HOXD10 expression is lost as a function of invasion and reintroduction of HOXD10 restores non-tumorigenic phenotypes in invasive breast cancer cells, suggesting that HOXD10 may play a role as a suppressor of tumor invasive growth." (PMID 25236186, 2014). "Interestingly, miR-7, which is inhibited by HOTAIR through the suppression of HoxD10, is downregulated in breast cancer CSCs and overexpression of miR-7 could both partially reverse EMT and decrease the size of the CSC population in breast cancer cell lines by suppressing STAT3 signalling." (PMID 28430163, 2017). "Given the crucial role of STARD13-, CDH5-, HOXD1-, and HOXD10-3’UTRs in breast cancer metastasis, we believe that STARD13-, CDH5-, HOXD1-, and HOXD10-3’UTRs could be therapeutic targets for the development of anti-metastatic strategy for breast cancer treatment in the near future." (PMID 26985770, 2016).